RNU7-7P (RNA, U7 small nuclear 7 pseudogene)
Synonyms: U7.7
Gene: Small nuclear RNA gene on chromosome X (38,608,215 to 38,608,276, forward strand). Ensembl gene ENSG00000238606.
Homologues: Orthologues: macaque U7 (97% identical). Paralogues in human: RNU7-14P (92% identical), RNU7-19P (92% identical), RNU7-28P (92% identical), RNU7-3P (92% identical), RNU7-47P (92% identical), RNU7-10P (90% identical), RNU7-11P (90% identical), RNU7-143P (90% identical), RNU7-20P (90% identical), RNU7-23P (90% identical), RNU7-34P (90% identical), RNU7-35P (90% identical), and 142 more.
Diseases named in the same sentence as RNU7-7P in open-access papers:
RNU7-7P is named in the same sentence as 1 disease in open-access papers, as found by Europe PMC text mining. Sharing a sentence is not in itself a finding about the gene and the disease.
RNU7-7P shares sentences with these, for which no sentence is quoted: infection (1 paper).